KCNQ1OT1 (KCNQ1 opposite strand/antisense transcript 1)
Synonyms: KvDMR1; KCNQ1-AS2; KvLQT1-AS; LIT1; NCRNA00012; KCNQ10T1; Kncq1
Gene: Long non-coding RNA gene on chromosome 11 (2,597,308 to 2,700,003, reverse strand). Ensembl gene ENSG00000269821.
Gene Ontology:
Biological process: heterochromatin formation
Cellular component: nucleolus
Diseases named in the same sentence as KCNQ1OT1 in open-access papers:
KCNQ1OT1 is named in the same sentence as 157 diseases in open-access papers, as found by Europe PMC text mining. Sharing a sentence is not in itself a finding about the gene and the disease. The quoted sentences say what the papers report.
colorectal cancer (41 papers, 2015 to 2025). A primary or metastatic malignant neoplasm that affects the colon or rectum. "After performing the ceRNA network construction and survival analysis, the lncRNA KCNQ1OT1 was found to be significantly upregulated in colorectal cancer tissues and associated with the survival of patients." (PMID 34630508, 2021). "Curcumin treatment effectively downregulates KCNQ1OT1 expression, hence restoring cisplatin resistance in colorectal cancer cells." (PMID 41322307, 2025). "Knockdown of lncRNA KCNQ1OT1 in colorectal cancer cells reduces CD620 expression and enhances the immune response of CD8 T cells." (PMID 38408075, 2024). "Long noncoding RNA KCNQ1OT1 upregulates the methotrexate resistance of colorectal cancer cells by inhibiting miR-760/PPP1R1B." (PMID 36726491, 2023). "Exosomal lncRNA KCNQ1OT1 derived from colorectal cancer cells promotes colorectal cancer immune escape through miR-30a-5p/USP22 regulated PD-L1 ubiquitination." (PMID 36358833, 2022). "For instance, lncRNA KCNQ1OT1/CD155 axis facilitates antitumor immune response by regulating T-cell depletion status in colorectal cancer; and lncRNA KCNQ1OT1 level is an indicator of patients' prognoses by reflecting the immune status of tumor tissue." (PMID 36245844, 2022). "For example, KCNQ1OT1, a long non-coding RNA, acts as an oncogene in colorectal cancer through the PI3K/AKT pathway, but was found here to be downregulated in GCA." (PMID 34804955, 2021). "KCNQ1OT1 has been reported to be involved in lung cancer, tongue cancer, glioma, colorectal cancer, bladder cancer, prostate cancer, and AML." (PMID 34404765, 2021). "We next analyzed the correlation between KCNQ1OT1 and clinical characteristics of patients with colorectal cancer." (PMID 32564010, 2020). "In this study, we investigated the mechanistic role and prognostic significance of lncRNA KCNQ1OT1 in colorectal cancer (CRC)." (PMID 32564010, 2020). "In this study, we investigated the mechanistic role and prognostic significance of the long coding RNA (lncRNA) KCNQ1OT1 in colorectal cancer (CRC)." (PMID 32564010, 2020). "It was reported that KCNQ1OT1 was upregulated and promoted tumor development in osteosarcoma, non-small cell lung cancer, colorectal cancer and so on." (PMID 32905431, 2020). "Quantitative real time PCR (qRT-PCR) analyses showed that KCNQ1OT1 expression was significantly higher in colorectal cancer samples compared to adjacent normal colorectal tissues (n=79)." (PMID 32564010, 2020). "Our study demonstrates that lncRNA KCNQ1OT1 is significantly upregulated in colorectal cancer tissues compared to adjacent normal colorectal tissues." (PMID 32564010, 2020). "Taken together, these findings demonstrate that KCNQ1OT1 modulates colorectal cancer proliferation by enhancing aerobic glycolysis through HK2." (PMID 32564010, 2020). "Next, we analyzed the relationship between lncRNA KCNQ1OT1 expression and survival outcomes in colorectal cancer patients." (PMID 32564010, 2020). "Correlation analysis between KCNQ1OT1 levels and clinicopathological features in colorectal cancer patients." (PMID 32564010, 2020). "We aimed to explore the mechanism of the KCNQ1OT1/miR‐760/PPP1R1B axis acting to regulate methotrexate (MTX) resistance of colorectal cancer (CRC)." (PMID 30997746, 2019). "Since KCNQ1OT1 was proved as the direct target of β-catenin signaling in colorectal cancer, the results indirectly revealed the potential interaction of KCNQ1OT1 and β-catenin." (PMID 29541443, 2018). "Here, we show that the KCNQ1OT1 transcriptional level was significantly increased in human colorectal cancer cells in which β-catenin was excessively accumulated in the nucleus." (PMID 26868975, 2016). "Here, we first investigated KCNQ1OT1 expression status in four colorectal cancer cell lines using quantitative reverse transcription PCR (qRT-PCR)." (PMID 26868975, 2016).
colorectal cancer (continued). "In this assay, crosslinking of β-catenin to the TCF binding site in the KCNQ1OT1 promoter in cells of the colorectal cancer cell lines HCT15 and SW480 was assayed." (PMID 26868975, 2016). "In the present study, we showed that KCNQ1OT1 transcription in colorectal cancer cell lines is driven by direct binding of β-catenin to its promoter region." (PMID 26868975, 2016). "We found that accumulation of nuclear β-catenin induced dysregulation of KCNQ1OT1 transcription in colorectal cancer cells." (PMID 26868975, 2016). "In the present study, we demonstrated that the mRNA expression of SLC22A18 and PHLDA2, which are regulated by KCNQ1OT1 lncRNA spreading, was increased by the knockdown of β-catenin in colorectal cancer cells." (PMID 26868975, 2016). "KCNQ1OT1 intensified cisplatin resistance in colorectal cancer cells via the miR-497/Bcl-2 pathway." (PMID 41322307, 2025). "In addition, ZNF146 was observed to be the downstream target of the LncRNA KCNQ1OT1, and it promoted the development of colorectal cancer." (PMID 37762228, 2023). "It has been observed that KCNQ1OT1 is highly expressed in colorectal cancer cells, and its potential mechanism could act as a sponge for miR-497 (a Bcl-2 inhibitory miRNA)." (PMID 36291546, 2022). "In contrast, overexpression of KCNQ1OT1 could reverse the anti-proliferative function of curcumin and increase Bcl-2 levels to promote cisplatin resistance in colorectal cancer cells." (PMID 36291546, 2022). "In addition, KCNQ1OT1 was also upregulated in colorectal cancer (CRC), which accelerates the proliferation, migration, and epithelial–mesenchymal transition (EMT) of CRC cells via regulating miR-217/ZEB1 axis." (PMID 34404765, 2021). "Next, we analyzed KCNQ1OT1 levels in several colorectal cancer cell lines." (PMID 32564010, 2020). "KCNQ1OT1 knockdown decreases aerobic glycolysis in colorectal cancer cells." (PMID 32564010, 2020). "Also, they showed KCNQ1OT1 was able to affect the chemosensitivity of colorectal cancer cell via targeting protein phosphatase 1 regulatory inhibitor subunit 1B (604399) through sponging MIR‐760." (PMID 31909901, 2020). "Next, to analyze if KCNQ1OT1 functions as an oncogenic lncRNA in colorectal cancer by regulating HK2 expression, we transfected KCNQ1OT1-knockdown HCT116 cells with the pcDNA3.1-HK2 plasmid and obtained HK2 levels that were similar to parental HCT116 cells as analyzed by western blotting." (PMID 32564010, 2020). "For example, KCNQ1OT1 was found overexpressed in methotrexate resistant colorectal cancer cells." (PMID 31909901, 2020). "These evidences suggested that KCNQ1OT1 transcription may be closely related to initiation and/or progression of colorectal cancer." (PMID 26868975, 2016). "Our evidence indicates that β-catenin signaling may contribute to development of colorectal cancer by functioning as a novel lncRNA regulatory factor via direct targeting of KCNQ1OT1." (PMID 26868975, 2016). "Furthermore, aberration of KCNQ1OT1 transcription was observed with a high frequency in colorectal cancers." (PMID 26868975, 2016). "Moreover, β-catenin affected the extent of KCNQ1OT1 lncRNA-coated territory in a dose-dependent manner, resulting in at least dysregulation of KCNQ1OT1-targeted genes in colorectal cancer." (PMID 26868975, 2016). "XIST, MALAT1, H19, and KCNQ1OT1 were ranked in the top four prediction list of colorectal cancer." (PMID 26278472, 2015). "Additionally, KCNQ1OT1 expression is upmodulated in methotrexate-resistant colorectal cancer cells, and KCNQ1OT1 silencing re-sensitizes resistant cells to methotrexate through downregulating cAMP-response element binding protein (CREB) and CREB-binding protein (CBP) levels." (PMID 35055115, 2022). "Hence, KCNQ1OT1 is a potential prognostic indicator and a therapeutic target in colorectal cancer." (PMID 32564010, 2020).
colorectal cancer (continued). "Thus, in vivo, β-catenin can directly regulate KCNQ1OT1 transcription suggesting that the regulation of KCNQ1OT1 lncRNA by β-catenin signaling may be involved in the multiple processes of colorectal cancer development." (PMID 26868975, 2016). "However, the molecular mechanism of the transcriptional regulation and the functional role of KCNQ1OT1 in colorectal cancer remain unclear." (PMID 26868975, 2016). "Curcumin treatment can effectively down-regulate KCNQ1OT1, thereby reversing the DDP resistance of colorectal cancer cells." (PMID 39039611, 2024). "DSCC1 is more upregulated in GCA than colorectal adenocarcinoma; KCNQ1OT1 and MXRA5 are downregulated in GCA, compared to other colorectal cancers." (PMID 40729214, 2024). "Either the tumor weight or tumor size was enlarged in mice overexpressing KCNQ1OT1 or XIST, indicating that KCNQ1OT1/XIST overexpression induced tumor growth in mice with colorectal cancer." (PMID 34521445, 2021). "We used quantitative real-time polymerase chain reaction (RT-qPCR) and western blot to detect the expression levels of lncRNA KCNQ1OT1 and the CD155 protein in colorectal cancer (CRC) tissues and cell lines." (PMID 33994860, 2021). "KCNQ1OT1 is highly expressed in colorectal cancer (CRC), and its high expression predicts an unfavorable prognosis; functionally, KCNQ1OT1 facilitates CRC cell growth and metastasis by modulating the miR-217/ZEB1 molecular axis." (PMID 33909822, 2021). "Kaplan-Meier survival curve analysis demonstrated that colorectal cancer patients with high KCNQ1OT1 levels showed significantly lower overall survival (OS) and disease-free survival (DFS) rates than those with low KCNQ1OT1 levels." (PMID 32564010, 2020). "QRT-PCR analysis showed significantly higher levels of KCNQ1OT1 in HCT116 and SW48 cell lines compared to other colorectal cancer cell lines." (PMID 32564010, 2020). "In our previous reports, we proved that lncRNA KCNQ1OT1 is up‐regulated in and serves as an oncogene while PGM5‐AS1 is down‐regulated and serves as a tumour suppressor in colorectal cancer." (PMID 31965704, 2020). "In our previous work, we have demonstrated lncRNA KCNQ1OT1 promoted EMT in colorectal cancer (CRC) by sponging miRNA217,22 and the KCNQ1OT1‐miRNA217 axis was included in the ceRNA network we built in this study." (PMID 31965704, 2020). "We further demonstrate that KCNQ1OT1 levels positively correlate with HK2 expression and prognosis in colorectal cancer patients." (PMID 32564010, 2020). "Nowadays, biological experiments have further linked mutations and dysregulations of some lncRNAs with the development and progression of colorectal cancer, such as HOTAIR, KCNQ1OT1, and MALAT1 in our training samples." (PMID 26061969, 2015). "Treated by curcumin, Lnc NBR2, Lnc KCNQ1OT1, Lnc PANDAR, and Lnc CCAT1 could prove to be potentially effective target molecules in the treatment progress of colorectal cancer." (PMID 36291546, 2022). "Notably, both of KCNQ1OT1 and SNHG1 were significantly up-regulated in tumor tissues and possessed excellent ability in distinguishing colorectal cancer patients." (PMID 33194594, 2020). "A gene set variation analysis (GSVA) indicated that the expression of the KCNQ1OT1 ceRNA network in colorectal cancer tissues and normal tissues were significantly different, not only in the TCGA-COAD dataset but also in three other GEO datasets used as validation." (PMID 34630508, 2021). "The tumor-promoting effect of lncRNA KCNQ1OT1 was through the autocrine effect of tumor cell-derived exosomes, which mediates the miR-30a-5p/USP22 pathway to regulate the ubiquitination of PD-L1 and inhibits CD8+ T-cell response, thereby promoting colorectal cancer development." (PMID 34350172, 2021).
colorectal cancer (continued). "Considering that KCNQ1OT1 as a regulator of autophagy was correlated with chemoresistance in some cancers like colorectal cancer and NSCLC24,28,29, we speculated elevated KCNQ1OT1 in IR-resistant cells might keep them from IR damage by the promotion of autophagy." (PMID 33082306, 2020). "KCNQ1 opposite strand/antisense transcript 1 (KCNQ1OT1) is a type of long chromatin-interacting lncRNA that has been widely reported to be a cancer promoter in various types of tumors such as non-small cell lung carcinoma, colorectal cancer, tongue cancer, and breast cancer." (PMID 32332718, 2020). "Earlier studies showed that KCNQ1OT1 promoted NSCLC progression by modulating miRNA-27b-3p/HSP90AA1 axis, and stimulated cholangiocarcinoma development via miR-140-5p/SOX4 axis, and facilitated the migration and EMT of colorectal cancer by forming a feedback loop with miR-217 and ZEB1." (PMID 32821247, 2020).
Beckwith-Wiedemann syndrome (23 papers, 2003 to 2025). Beckwith-Wiedemann syndrome (BWS) is a genetic disorder characterized by overgrowth, tumor predisposition and congenital malformations. "LncRNA Kcnq1ot1 has been known to be associated with Beckwith-Wiedemann Syndrome and glioma malignancy, and depressing lung adenocarcinoma chemoresistance to paclitaxel." (PMID 29628875, 2018). "Decreased KCNQ1OT1 methylation has been identified in tumour development and the imprinting disorder Beckwith-Wiedemann syndrome which is associated with tumour predisposition." (PMID 26347357, 2015). "In Beckwith-Wiedemann Syndrome (BWS) the loss of methylation (LOM) at the KCNQ1OT1 on chromosome 11p15.5 (within imprinting center 2 [IC2]) is maternally imprinted and represents the cause in 50–60% of patients." (PMID 40730975, 2025). "Some studies showed that downregulated KCNQ1OT1 in the placenta was related to the selective intrauterine growth restriction of monozygotic twins, Beckwith-Wiedemann syndrome (BWS), and Silver-Russell syndrome (SRS)." (PMID 35938169, 2022). "Nevertheless, in 50% of Beckwith-Wiedemann syndrome sporadic loss of methylation in IC2 is observed and KCNQ1OT1 expression becomes biallelic while the transcription of nearby genes is absent." (PMID 30871545, 2019). "LncRNA KCNQ1OT1 was not only abnormally expressed from the chromosomes in most patients with Beckwith-Wiedemann syndrome, but also played an important role in colorectal carcinogenesis." (PMID 29970910, 2018). "Similarly, the lncRNA KCNQ1OT1, which is involved in imprinting in Beckwith-Wiedemann syndrome by silencing lineage-specific transcription through chromatin regulation, is also enriched on histone H3 over input, as expected." (PMID 31862000, 2019). "For example, most of the individuals affected by Beckwith-Wiedemann syndrome (BWS) have altered DNA methylation of either the H19-IGF2:IG-DMR (also known as IC1) or the KCNQ1OT1:TSS-DMR (also known as IC2) both located on chromosome 11p15.5 that regulate two independent gene clusters." (PMID 31829238, 2019).
osteosarcoma (23 papers, 2020 to 2025). A usually aggressive malignant bone-forming mesenchymal neoplasm, predominantly affecting adolescents and young adults. "KCNQ1OT1 expression is increased in osteosarcoma patient tissue and is associated with OS progression and decreased overall survival." (PMID 34827600, 2021). "The downregulation of KCNQ1OT1 inhibits proliferation, invasion, and drug resistance in osteosarcoma cells through miR-129-5p-mediated LARP1 regulation." (PMID 40018039, 2025). "lncRNA KCNQ1OT1 sponged miR-34c-5p in the capacity of a competitive endogenous RNA (ceRNA), hence inhibiting the development of osteosarcoma cells in vivo, and prevented the in vivo proliferation of osteosarcoma cells by directly targeting its 3’Untranslated." (PMID 39346921, 2024). "In another in vitro investigation, lncRNA KCNQ1OT1 was found to stimulate cell proliferation and inhibit apoptosis while promoting osteosarcoma cell development in vivo." (PMID 39346921, 2024). "As reported by previous studies, KCNQ1OT1 has been demonstrated to sponge miR-34c-5p in osteosarcoma, miR-125b-5p in ovarian cancer, miR-26a-5p in ischemia reperfusion." (PMID 38057885, 2023). "lncRNA KCNQ1OT1 sponges miR-34c-5p to enhances osteosarcoma progression by ALDOA-enhanced aerobic glycolysis." (PMID 35342412, 2022). "Some investigators have suggested that KCNQ1OT1 can facilitate cell proliferation, invasion, and metastasis in multiple types of cancers, such as prostate cancer, hepatocellular carcinoma, and osteosarcoma." (PMID 34802433, 2021). "Dramatically, KCNQ1OT1 was up-regulated in tumor tissues and cells of colon cancer, osteosarcoma, gastric cancer, and NSCLC." (PMID 33345272, 2021). "LncRNA KCNQ1OT1 has been ascertained as a sponge of miR-4458, thus facilitating osteosarcoma cell growth via upregulating CCND2." (PMID 34863279, 2021). "In this study, we explored the effect of KCNQ1OT1 on the development of osteosarcoma and its potential mechanisms." (PMID 32953888, 2020). "The mRNA expression of KCNQ1OT1 in tumor tissues and adjacent tissues of 30 osteosarcoma patients was analyzed." (PMID 32953888, 2020). "In the present research, we aimed to explore the effect of KCNQ1OT1 on osteosarcoma and further explore the special molecular mechanism." (PMID 32953888, 2020). "In the present study, we focused on the effect of KCNQ1OT1 on cell proliferation, invasion, and drug resistance in osteosarcoma as well as the special regulatory mechanisms." (PMID 32953888, 2020). "The expression of KCNQ1OT1 was analyzed in tumor and adjacent tissues of 30 patients with osteosarcoma by RT-PCR." (PMID 32953888, 2020). "Results suggested that the knockdown of KCNQ1OT1 inhibited the cell proliferation invasion and drug resistance in osteosarcoma, and miR-129-5p was a target of KCNQ1OT1." (PMID 32953888, 2020). "KCNQ1OT1 exerts an important role in various cancers, but its role in osteosarcoma (OS) and the potential mechanism remain to be clarified." (PMID 32953888, 2020). "Roles of KCNQ1 opposite strand/antisense transcript 1 (KCNQ1OT1) in cancers including osteosarcoma and colon cancer have been previously reported." (PMID 31909901, 2020). "KCNQ1OT1 was reported to be significantly more expressed in osteosarcoma than in adjacent tissues." (PMID 35432529, 2022). "This review summarizes recent literature related to the biological functions and molecular mechanisms of KCNQ1OT1 in various human cancers, including colorectal, bladder, breast, oral, melanoma, osteosarcoma, lung, glioma, ovarian, liver, acute myeloid leukemia, prostate, and gastric." (PMID 34827600, 2021). "Similarly, upregulated lncRNA Potassium Voltage-Gated Channel Subfamily Q Member 1 Overlapping Transcript 1 (KCNQ1OT1) facilitates proliferation and decreases the apoptosis of osteosarcoma cells." (PMID 33652661, 2021). "KCNQ1OT1-siRNA inhibited the proliferation, invasion, and drug resistance of osteosarcoma cells." (PMID 32953888, 2020).